NR3C1 (nuclear receptor subfamily 3 group C member 1)
Diseases named in the same sentence as NR3C1 in open-access papers (continued):
Sharing a sentence is not in itself a finding about the gene and the disease.
post-traumatic stress disorder (35 papers, 2009 to 2025). An anxiety disorder precipitated by an experience of intense fear or horror while exposed to a traumatic (especially life-threatening) event. "A negative association between percentage of methylation on the NR3C1 gene’s promoter region and post-traumatic stress disorder has been established in prior studies of combat veterans who clearly experienced violence but whose early life-histories are unclear." (PMID 26074844, 2015). "In adults, findings have been more variable: some studies have reported increased NR3C1 methylation following early-life adversity, while others have found hypomethylation associated with suicide or post-traumatic stress disorder (PTSD)." (PMID 41179817, 2025). "Of further interest, three studies have shown that methylation of NR3C1 exon 1F can predict health outcomes, whether predicting quality of movement and attention at birth, response to psychotherapy in adults with posttraumatic stress disorder or response to threat-associated stress in adult females." (PMID 25229548, 2014). "The upregulation of NR3C1 expression, as observed after weaning in piglets fed skimmed cow milk, has been noted in animals that experienced early life stress and in humans diagnosed with posttraumatic stress disorder (PTSD)." (PMID 37122716, 2023). "Indeed, research has shown differential effects of maternal and paternal diagnosis of posttraumatic stress disorder on their children’s NR3C1 methylation." (PMID 31000782, 2019). "In addition, adults with post-traumatic stress disorder had decreased DNA methylation at the same or alternate NR3C1 promoters." (PMID 25229548, 2014). "Changes in NR3C1 methylation, particularly in peripheral blood monocytes (PBMCs) that correlate with the severity of neuropsychiatric symptoms are found in parents and offspring with post-traumatic stress disorder (PTSD), borderline personality disorder, MDD, and other disorders." (PMID 37106766, 2023). "Other examples include epigenetic modulation of glucocorticoid receptors in patients with post-traumatic stress disorder (PTSD), where the transmission to the offspring was explained by the transmission of epigenetic processes such as the methylation status of the glucocorticoid receptor gene NR3C1." (PMID 34298869, 2021).
diabetes (27 papers, 2006 to 2026). "Another study found that NR3C1 enhancement up-regulated FTO protein levels in β-cells and that the specific FTO inhibitor Dac51 effectively rescued NR3C1-induced β-cell failure, hyperglycemia, and glucose intolerance in diabetes models." (PMID 41585810, 2025). "TF prediction analysis showed that NR3C1, TEAD and TFs that cooperate with YAP-TEAD, such as Klf4, SP1, AP1, MYC and ZEB1, were enriched in the DEGs of the diabetes vs. control comparison." (PMID 34970541, 2021).
Hypertension (27 papers, 2011 to 2025). The presence of chronic increased pressure in the systemic arterial system. "According to the RGD database, both genes encoding transcription factors CREB1 and NR3C1 are associated with hypertension." (PMID 39594444, 2024). "Literature suggests that variants in NR3C1 are associated with the AD glucocorticoid resistance characterized by impaired cortisol signalling, clinically resulting in hypoglycaemia, hypertension, metabolic alkalosis, chronic fatigue and female infertility." (PMID 39298385, 2024). "Studies have revealed that NR3C1 polymorphisms can affect blood pressure regulation and cardiovascular function, and variations in this gene have been linked to an increased risk of hypertension." (PMID 37571339, 2023). "Additionally, variants of NR3C1 have been detected in 5% of patients with bilateral adrenal hyperplasia associated with hypercortisolemia and hypertension, emphasizing the importance of adrenal hyperplasia in the diagnosis of GRS." (PMID 40452801, 2025). "Likewise, hypermethylation of the NR3C1 promoter has been observed in response to stress during early life stages, leading to altered expression of the glucocorticoid receptor, a change linked to the development of hypertension, diabetic nephropathy, and chronic kidney disease." (PMID 41226547, 2025). "The emergence and progression of hypertension have been linked to the genes HIF1A, CYP11B1, and NR3C1." (PMID 37571339, 2023). "A multitargeted interaction-based degree algorithm and a phylogenetic tree of pathways showed that the NR3C1, REN, PPARG, and CYP11B1 hub genes were consistently modulated by Υ-sitosterol to reduce hypertension and related risk factors." (PMID 37571339, 2023). "Although a relatively high number of human subjects suffering from glucocorticoid resistance and carrying NR3C1 mutations exhibit adrenal hyperplasia, this clinical feature may not be a prerequisite to develop hypertension." (PMID 35732960, 2022). "Moreover, it is suggested that increased tissue sensitivity to cortisol due to polymorphisms in glucocorticoid receptor (GR) gene (NR3C1, Nuclear Receptor Subfamily 3 Group C Member 1) is related to the criteria of MetS (e.g., visceral obesity, hypertension), despite normal HPA axis activity." (PMID 34179504, 2021). "NR3C1, REN, PPARG, and CYP11B1 were identified as critical targets (36-degree value) in the network for hypertension progression because of this conformity." (PMID 37571339, 2023).
hypercortisolemia (26 papers, 2011 to 2025). "Diagnosing asymptomatic hypercortisolism involves several endocrinological and imaging tests, culminating in the analysis of the NR3C1 gene to identify underlying abnormalities." (PMID 40452801, 2025). "To explore the potential effect of hypercortisolism on DNA methylation of the NR3C1 gene, we analysed specifically DNA methylation of this gene." (PMID 28300138, 2017). "To explore the potential effect of hypercortisolism on NR3C1 DNA methylation specifically, we analysed methylation in this gene and found that 15 out of 49 probes annotated to the NR3C1 gene were differentially methylated in cases as compared to controls." (PMID 28300138, 2017). "If the variants in our study are found to be associated with structural or functional impairment of NR3C1 and defective binding to circulating cortisol, it could potentially explain the MDD-related and T2D-related traits associated with hypercortisolism." (PMID 36233250, 2022). "We suggest that NR3C1 sequencing be completed in patients with persistent biochemical hypercortisolism in the absence of clinical signs/symptoms of Cushing syndrome and in patients with a known or suspected family history of glucocorticoid resistance." (PMID 39850725, 2025). "A mutation of the glucocorticoid receptor gene (GRα or NR3C1) causes cortisol and ACTH hypersecretion, without clinical evidence of hypercortisolism but with manifestations of androgen and mineralocorticoid excess." (PMID 37360895, 2021). "In humans, glucocorticoid resistance (OMIM 615962) induces hypercortisolemia but patients are not Cushingoid due to loss of function mutations in NR3C1, the gene encoding the glucocorticoid receptor (GR)." (PMID 30038578, 2018). "The diagnostic evaluation for GRS involves documentation of biochemical hypercortisolism with elevated or inappropriately normal ACTH levels, reflecting central resistance to glucocorticoid signaling, testing for mineralocorticoid and androgen excess, and genetic sequencing of the NR3C1 gene." (PMID 39850725, 2025). "The inactivating heterozygous mutations of the NR3C1/GR gene are the cause of congenital primary generalized GC resistance or Chrousos ́ syndrome (OMIM #615962), a rare genetic condition characterized by hypercortisolism without signs of Cushing’s syndrome." (PMID 34576214, 2021).
COVID-19 (25 papers, 2021 to 2025). A disease caused by infection with severe acute respiratory syndrome coronavirus 2. "Nevertheless, our finding is in accordance with a recent study determining the effect of NR3C1 gene variants on the course of the disease in patients with COVID-19 using the PCR-RFLP method." (PMID 38187222, 2024). "The combination of these effects may explain why in our study patients with COVID-19 with chronic diseases and NR3C1 polymorphism may have needed prolonged hospital care." (PMID 39135792, 2024). "Given this potential association between post-corticosteroid IL-6 levels and COVID-19 severity, we hypothesized that the glucocorticoid receptor (GR or NR3C1) may be coupled to IL-6 expression in specific cell types that govern cytokine release syndrome (CRS)." (PMID 33723251, 2021). "The differential NR3C1 signaling across T cell phenotypes in COVID-19 patients treated with DEXA has practical implications for clinical management and drug development." (PMID 39975141, 2025). "This understanding motivated us to apply Incytr to infer NR3C1 signaling patterns across T cell subtypes in COVID-19 patients treated with DEXA." (PMID 39975141, 2025). "The study demonstrated that NR3C1 expression was higher in mild COVID-19 cases and lower in severe cases." (PMID 38187222, 2024). "Our findings bring novel evidence of NR3C1 rs6198, GSTP1 rs1695, and CYP3A4 rs35599367 polymorphisms having impact on COVID-19 severity, the course of the disease, and the outcome of treatment with dexamethasone and methylprednisolone." (PMID 39135792, 2024). "COVID-19 patients with well-response to steroid therapy have higher NR3C1 expression than the poor-response group." (PMID 38187222, 2024). "The current study is among the first to show a greater impact of exposure to the COVID-19 pandemic on levels of maternal and infant methylation of target stress-related genes (i.e., NR3C1 and SLC6A4) in late gestation, as compared to earlier exposures." (PMID 36114180, 2022). "Given that dexamethasone appears to reduce mortality among only severe cases of COVID-19, we finally asked how NR3C1 and IL-6 co-expression varies between mild and severe disease." (PMID 33723251, 2021). "Thus, we believe that our interesting findings should be further studied in the future in order to develop our understanding of the roles of NR3C1 and its related genes, particularly in COVID-19 conditions." (PMID 38187222, 2024). "The study suggested that the presence of NR3C1 was not related to severe cases of COVID-19 yet associated with longer glucocorticoid therapy." (PMID 38187222, 2024). "Therefore, we suggested that the fascinating findings we have uncovered warrant deeper exploration to expand our comprehension of the roles of NR3C1 and its related genes, especially with regard to COVID-19." (PMID 38187222, 2024). "The presence of polymorphic allele of NR3C1 rs6198, ABCB1 rs2032582 or GSTP1 rs1695 polymorphism could predict poorer course of COVID-19 and also poorer treatment outcome." (PMID 39135792, 2024). "Indeed, corticosteroids have been shown to suppress CRS, and NR3C1 has been shown to transcriptionally downregulate many inflammatory cytokines overexpressed in COVID-19 patients, such as CCL2, IL1B, and IL6." (PMID 34163359, 2021). "In bronchoalveolar lavage fluid (BALF) of COVID-19 patients, both macrophages and T cells strongly expressed NR3C1, while plasma cells, neutrophils, and the recovered epithelial populations showed lower levels of NR3C1 expression (nferX platform single cell app)." (PMID 33723251, 2021). "A study has shown that prenatal stress related to COVID-19 is associated with methylation of the gene in infants and that it is possible that the COVID-19-related stress exposure during this special period may also exert effects on the NR3C1 DNA methylation in pregnant women." (PMID 36091061, 2022).
COVID-19 (continued). "Similarly, in a study of peripheral blood samples from healthy donors (n = 6) and COVID-19 patients between days 2 and 16 of symptom onset (n = 7), NR3C1 was appreciably expressed in diverse immune cell types including T cells, B cells, dendritic cells, monocytes, and plasmacytoid dendritic cells." (PMID 33723251, 2021). "To answer this, we assessed NR3C1 and IL-6 expression levels in each recovered BALF cell population between cases of mild COVID-19 (n = 3) and severe COVID-19 (n = 6), along with healthy controls (n = 3)." (PMID 33723251, 2021). "Accordingly, our observation that NR3C1 expression is decreased in severe COVID-19 patients compared to mild COVID-19 patients may reflect a pathologic downregulation of this endogenous immunomodulatory system which can be restored pharmacologically via corticosteroid-mediated agonism of NR3C1." (PMID 33723251, 2021). "Given that patients with severe COVID-19 are often treated with immune suppressants, ex vivo expanded SARS-CoV-2 specific T cells can be additionally manipulated by CRISPR-Cas9 gene-editing methods to render them resistant to glucocorticoids by inactivating the glucocorticoid receptor gene (NR3C1)." (PMID 35011627, 2021).
Insulin resistance (23 papers, 2009 to 2025). Increased resistance towards insulin, that is, diminished effectiveness of insulin in reducing blood glucose levels. "NR3C1 gene genetic variation may contribute to higher body mass index (BMI), elevated plasma lipid levels, insulin resistance, and HT, which are considered atherosclerosis risk factors." (PMID 36009459, 2022). "Previous studies from our PTSD Systems Biology Consortium reported associations between PTSD and insulin resistance, inflammation, reduced mitochondrial copy number, and lower methylation of the glucocorticoid receptor (NR3C1) gene in the same cohorts assessed in the present study." (PMID 31322414, 2019). "In a study conducted in Brazil, an association was discovered between peripheral methylation of the NR3C1 gene and glycemic levels, as well as insulin resistance." (PMID 38633601, 2024). "Peripheral blood was collected and evaluated for cortisol levels, glycemia, lipid profile, and insulin resistance; methylation of CpGs 40–47 of the 1F region of the NR3C1 gene was also measured." (PMID 38633601, 2024). "Variants in the NR3C1 gene have been reported to contribute to metabolic syndrome in patients with PCOS and to insulin resistance, which is a feature of PCOS indirectly contributing to increased free androgen blood levels via reduction of the sex-hormone binding globulin blood levels." (PMID 38217051, 2024).
Sepsis (22 papers, 2008 to 2025). Sepsis is defined as life-threatening organ dysfunction caused by a dysregulated host response to infection. "The TT genotype of rs6198 SNP in the NR3C1 gene is associated with higher 30-day mortality in sepsis patients and increased expression of the GRα isoform." (PMID 40634451, 2025). "The rs6198 SNP in the NR3C1 gene is associated with 30-day mortality in sepsis patients and correlates with increased expression of the GRα isoform." (PMID 40634451, 2025). "Our study demonstrates that the presence of the NR3C1 rs6198 SNP influences survival in sepsis." (PMID 40634451, 2025). "However, the impact of rs6198 SNP within NR3C1 in sepsis, specifically its effects on the differential expression of GRα versus GRβ, and consequently on sepsis outcomes, has not been investigated." (PMID 40634451, 2025).
Cushing syndrome (20 papers, 2012 to 2025). Cushing's syndrome (CS) encompasses a group of hormonal disorders caused by prolonged and high exposure levels to glucocorticoids that can be of either endogenous (adrenal cortex production) or exogenous (iatrogenic) origin. "Of interest, a study reported that the NR3C1 variant was associated with reduced risk of T2D in patients with Cushing syndrome." (PMID 36233250, 2022). "A key element in this context is the glucocorticoid receptor (NR3C1), which, when activated by glucocorticoids such as cortisol, is considered to mediate their effects, including those of Cushing's syndrome in the case of chronic activation." (PMID 33724179, 2021).
rheumatoid arthritis (19 papers, 2007 to 2023). A chronic, systemic autoimmune disorder characterized by inflammation in the synovial membranes and articular surfaces. "In patients with rheumatoid arthritis, four polymorphisms in the NR3C1 gene were identified as clinically relevant." (PMID 35120172, 2022).
schizophrenia (19 papers, 2007 to 2025). A major psychotic disorder characterized by abnormalities in the perception or expression of reality. "Schizophrenia and psychosis are well associated with the methylation of NR3C1 at various stages and any gender differences in methylation for this gene should be an important consideration for future genetic studies on schizophrenia." (PMID 37108291, 2023). "However, NR3C1 methylation in blood samples was reported to be associated with schizophrenia, in females, supporting its role in the pathophysiology of schizophrenia." (PMID 33673722, 2021). "Moreover, variants of the glucocorticoid receptor gene (NR3C1) are linked with schizophrenia and bipolar disorder." (PMID 23503168, 2013). "NR3C1 methylation at exons 1B, 1D, and 1F were found positively correlated with schizophrenia in females, while methylation at exons 1D, 1F, and 1H were found correlated with schizophrenia in males." (PMID 37108291, 2023). "We conducted a systematic gene expression meta-analysis of FKBP5 and NR3C1 in cerebellum samples of individuals with schizophrenia vs. healthy controls." (PMID 33673722, 2021). "We detect up-regulation of FKBP5 and down-regulation of NR3C1 in the cerebellum of the individuals with schizophrenia." (PMID 33673722, 2021). "Patients with schizophrenia-spectrum disorders show altered levels of NR3C1 methylation that are significantly lower in first-episode psychosis patients and significantly higher in SCZ-AR patients." (PMID 33284958, 2021). "FKBP5 and NR3C1 differential expression was examined using a publicly available gene expression dataset of whole blood samples of 13 patients with schizophrenia and 8 controls." (PMID 33673722, 2021). "Taking into account these research gaps, we aimed to investigate the levels of NR3C1 methylation in acutely relapsed schizophrenia patients (SCZ-AR), FEP patients, individuals at familial high risk of psychosis (FHR-P), and healthy controls." (PMID 33284958, 2021). "In order to explore genetic variation within the NR3C1 gene in schizophrenia and bipolar disorder, the cohort was genotyped for 11 functional or promoter NR3C1 SNPs." (PMID 22427805, 2012). "NR3C1 methylation patterns are also altered in schizophrenia and BD, which may contribute to neuroendocrine dysfunction in these disorders, although these findings are more variable." (PMID 41234420, 2025). "While FKBP5 was found to be up-regulated in schizophrenia, NR3C1 was detected to be down-regulated." (PMID 33673722, 2021). "Altogether, these findings suggest that methylation of the NR3C1 gene might increase with subsequent exacerbations of schizophrenia." (PMID 33284958, 2021). "Increase in the level of NR3C1 methylation might account for cognitive decline observed in schizophrenia." (PMID 33284958, 2021). "In addition, in order to explore a potential role of FKBP5 and NR3C1 as biomarkers, we performed differential expression analysis of the two genes using a blood samples cohort of 13 individuals with schizophrenia and 8 controls." (PMID 33673722, 2021). "Moreover, it has recently been found that patients with schizophrenia may have a different profile of NR3C1 methylation compared with healthy controls." (PMID 33284958, 2021). "One study, although limited in sample size, suggested that NR3C1 mRNA might be decreased in the dorso-lateral prefrontal cortex of schizophrenia cases, relative to controls, while among schizophrenia cases, it might be increased in suicide-positive vs suicide-negative subjects." (PMID 32754072, 2020). "For example, methylation of NR3C1, BDNF, and FKBP5 can differentiate subtypes of MDD, PTSD, or schizophrenia, help to identify stress-responsiveness compared with neurodevelopmental forms of illness, and be used as predictors of risk and resilience." (PMID 41234420, 2025).